HRH1 (histamine receptor H1)
Description:
G protein-coupled receptor for histamine, a biogenic amine that functions as an immune modulator and a neurotransmitter. Through the H1 receptor, histamine mediates the contraction of smooth muscles and increases capillary permeability due to contraction of terminal venules. Also mediates neurotransmission in the central nervous system and thereby regulates circadian rhythms, emotional and locomotor activities as well as cognitive functions (By similarity).
Synonyms: H1-R; H1R; HH1R; hisH1
Tractability: Small molecule: an approved drug acts on it; a structure with a bound ligand is known; a high-quality ligand is known; it has a binding pocket of medium quality; it belongs to a druggable protein family. Antibody: UniProt places it where antibodies can reach, with high confidence; its Gene Ontology location is reachable by antibodies, with high confidence; UniProt predicts a signal peptide or a membrane-spanning region; the Human Protein Atlas places it where antibodies can reach. PROTAC: ubiquitination databases record sites on it; a small molecule that binds it is known.
Target class: Family A G protein-coupled receptor; Small molecule receptor (family A GPCR); Histamine receptor; Membrane receptor; Monoamine receptor
Chemical probes: CHLORPHENIRAMINE, FEXOFENADINE, PD084515
Safety:
Unwanted effects reported when the protein is acted on. In parentheses: how it was acted on, where the effect was seen, and who reports it.
sedation (ClinPGx; Lynch et al. (2017): inhibition, acute dosing, nervous system, immune, cardiovascular, gastrointestinal; Bowes et al. (2012): inhibition, cardiovascular system, immune)
bronchoconstriction (Lynch et al. (2017): activation, acute dosing, nervous system, immune, cardiovascular, gastrointestinal; Bowes et al. (2012): activation, cardiovascular system, immune)
decreased blood pressure (Bowes et al. (2012): activation, cardiovascular system, immune; Lynch et al. (2017): activation, acute dosing, nervous system, immune, cardiovascular, gastrointestinal)
increased body weight (Lynch et al. (2017): inhibition, acute dosing, nervous system, immune, cardiovascular, gastrointestinal; Bowes et al. (2012): inhibition, cardiovascular system, immune)
abdominal cramps (activation, acute dosing; nervous system, immune, cardiovascular, gastrointestinal; source: Lynch et al. (2017))
allergic responses of flare, flush and wheal (activation; cardiovascular system, immune; source: Bowes et al. (2012))
cardiac arrhythmia (inhibition, acute dosing; nervous system, immune, cardiovascular, gastrointestinal; source: Lynch et al. (2017))
decreased allergic responses (inhibition; cardiovascular system, immune; source: Bowes et al. (2012))
decreased convulsions (activation, acute dosing; nervous system, immune, cardiovascular, gastrointestinal; source: Lynch et al. (2017))
decreased gastrointestinal transit (inhibition, acute dosing; nervous system, immune, cardiovascular, gastrointestinal; source: Lynch et al. (2017))
decreased inflammation (inhibition, acute dosing; nervous system, immune, cardiovascular, gastrointestinal; source: Lynch et al. (2017))
decreased pain (inhibition, acute dosing; nervous system, immune, cardiovascular, gastrointestinal; source: Lynch et al. (2017))
decreased/increased blood pressure (inhibition, acute dosing; nervous system, immune, cardiovascular, gastrointestinal; source: Lynch et al. (2017))
diarrhea (activation, acute dosing; nervous system, immune, cardiovascular, gastrointestinal; source: Lynch et al. (2017))
facial swelling (activation, acute dosing; nervous system, immune, cardiovascular, gastrointestinal; source: Lynch et al. (2017))
flushing (activation, acute dosing; nervous system, immune, cardiovascular, gastrointestinal; source: Lynch et al. (2017))
increased convulsions (inhibition, acute dosing; nervous system, immune, cardiovascular, gastrointestinal; source: Lynch et al. (2017))
increased drinking (activation, acute dosing; nervous system, immune, cardiovascular, gastrointestinal; source: Lynch et al. (2017))
increased heart rate (inhibition, acute dosing; nervous system, immune, cardiovascular, gastrointestinal; source: Lynch et al. (2017))
increased locomotor activity (inhibition, acute dosing; nervous system, immune, cardiovascular, gastrointestinal; source: Lynch et al. (2017))
increased pain (activation, acute dosing; nervous system, immune, cardiovascular, gastrointestinal; source: Lynch et al. (2017))
increased QTc interval (inhibition, acute dosing; nervous system, immune, cardiovascular, gastrointestinal; source: Lynch et al. (2017))
increased sleep (inhibition, acute dosing; nervous system, immune, cardiovascular, gastrointestinal; source: Lynch et al. (2017))
inflammation (activation, acute dosing; nervous system, immune, cardiovascular, gastrointestinal; source: Lynch et al. (2017))
scratching (activation, acute dosing; nervous system, immune, cardiovascular, gastrointestinal; source: Lynch et al. (2017))
skin rash (activation, acute dosing; nervous system, immune, cardiovascular, gastrointestinal; source: Lynch et al. (2017))
sweating (activation, acute dosing; nervous system, immune, cardiovascular, gastrointestinal; source: Lynch et al. (2017))
tongue swelling (activation, acute dosing; nervous system, immune, cardiovascular, gastrointestinal; source: Lynch et al. (2017))
Gene: Protein-coding gene on chromosome 3 (11,137,093 to 11,263,557, forward strand). Ensembl gene ENSG00000196639.
Subcellular location: Cell membrane
Subcellular location (Human Protein Atlas): Plasma membrane; Cytosol
Pathways (Reactome):
Signal Transduction: G alpha (q) signalling events; Histamine receptors
Gene Ontology:
Molecular function: histamine receptor activity; protein binding; G protein-coupled receptor activity
Biological process: cellular response to histamine; G protein-coupled receptor signaling pathway; chemical synaptic transmission; G protein-coupled receptor signaling pathway, coupled to cyclic nucleotide second messenger; inflammatory response; phospholipase C-activating G protein-coupled receptor signaling pathway; positive regulation of vasoconstriction; regulation of vascular permeability
Cellular component: plasma membrane; dendrite; membrane; synapse
Genetic constraint (gnomAD): Loss-of-function variants: 6 observed, 11.02 expected, observed/expected ratio (o/e) 0.54, 90% interval 0.3 to 1.07. The upper end of that interval is the gene's LOEUF score, 1.07, which puts it in group 4 of 6, group 1 being the genes least tolerant of losing a copy. Missense variants: 514 observed, 644.17 expected, observed/expected ratio (o/e) 0.8, 90% interval 0.74 to 0.86. Synonymous variants: 242 observed, 249.51 expected, observed/expected ratio (o/e) 0.97, 90% interval 0.87 to 1.08.
Homologues: Orthologues: chimpanzee HRH1 (99% identical), macaque HRH1 (95% identical), dog HRH1 (86% identical), pig HRH1 (85% identical), rat Hrh1 (79% identical), mouse Hrh1 (78% identical), guinea pig HRH1 (72% identical), tropical clawed frog hrh1 (56% identical), Drosophila melanogaster mAChR-C (17% identical). Paralogues in human: CHRM5 (25% identical), CHRM1 (24% identical), CHRM3 (24% identical), CHRM4 (23% identical), CHRM2 (23% identical), HTR1A (23% identical), HTR1D (23% identical), HTR4 (22% identical), DRD3 (21% identical), DRD4 (20% identical), HRH3 (20% identical), HRH2 (20% identical), and 13 more.
Diseases named in the same sentence as HRH1 in open-access papers:
HRH1 is named in the same sentence as 158 diseases in open-access papers, as found by Europe PMC text mining. Sharing a sentence is not in itself a finding about the gene and the disease. The quoted sentences say what the papers report.
Allergy (55 papers, 2010 to 2025). An allergy is an immune response or reaction to substances that are usually not harmful. "Loratadine and its primary metabolite, desloratadine, are potent antagonists of the human histamine receptor H1 (HRH1) and were originally intended to treat allergies and allergic rhinitis." (PMID 39886963, 2025). "Our previous study demonstrated that targeting histamine/HRH1 axis only partially reversed allergy-induced immunotherapy resistance." (PMID 36564797, 2022). "Expression of HRH-1 was significantly lower after stimulation with osthole compared to PBMCs cultured with histamine in the control and allergy groups." (PMID 30620999, 2019). "In total, 23 of the 151 compounds predicted to be effective against LSC in our in silico analysis are known to target HRH1, including anti-allergy drugs, tricyclic antidepressants and antipsychotic drugs." (PMID 29921955, 2018). "However, antihistamines can competitively bind to HRH1, which alleviates histamine-induced allergies." (PMID 39037273, 2024). "Our previous study found that the allergy mediator histamine could suppress tumor growth, and induce immunotherapy resistance via binding to histamine receptor H1 on macrophages, and anti-histamine therapy could synergistically enhance efficacy of ICB therapy." (PMID 36564797, 2022). "CLM, as a histamine HRH1 antagonist, is commonly used to treat the allergic diseases." (PMID 33437198, 2021). "Furthermore, after cellular stimulation with histamine, we observed an increase in HRH-1 mRNA levels in both the control and allergy groups, and COX-2 and EP2 only in the allergy group." (PMID 30620999, 2019). "The ABCB5-positive fraction also has an upregulation of Histamine Receptor 1 (HRH1), which regulates allergic responses in nasal and corneal epithelial cells, while non-competitive histamine antagonist (H1-receptor) is proposed for the treatment of allergy affecting the ocular surface." (PMID 37443766, 2023). "Their comprehensive study elucidated the anti-SARS-CoV-2 potential of different HRH1 antagonists, providing diverse options for SARS-CoV-2-infected individuals with distinct types of allergies." (PMID 39037273, 2024). "Histamine receptors are classified into four subtypes, with HRH1 and HRH2 being targets of anti-allergy and antiulcer drugs, respectively." (PMID 36246574, 2022). "First of all, we demonstrated that the basal expression levels of HRH-1, IL-1RI, COX-2, and EP2 mRNA were lower in the control compared to the allergy group." (PMID 30620999, 2019). "After three days of incubation, we detected that HRH-1, IL-1RI, COX-2, and EP2 receptors showed significantly higher expression in the allergy group compared to control (p < 0.0001)." (PMID 30620999, 2019). "The ad hoc prescription of H1‐antihistamines for mild and/or nonspecific allergy symptom management in infrequent users might account for the trend of decreased mortality risk by reversing malignancy‐specific immune evasion and ICI resistance via the histamine–HRH1 axis." (PMID 39791941, 2025).
allergic rhinitis (29 papers, 2012 to 2025). Inflammation of the nasal mucous membranes caused by an IgE-mediated response to external allergens. "Apart from association of this receptor in allergic rhinitis, causing tinnitus, snoring and rhinorrhea, recent studies indicated elevated expression of HRH1 in patients with autism spectrum disorder." (PMID 32050523, 2020). "The released histamines triggered by exogenous allergens bind to HRH1, resulting in the induction of allergic rhinitis and allergic lung responses." (PMID 39037273, 2024).
asthma (17 papers, 2005 to 2026). "Histamine H1 receptor (HRH1) and E-cadherin are highly expressed on cultured M2 cells and on M2 macrophages from broncho-alveolar lavage fluid (BALF) of asthma patients, serving as auxiliary markers; Ym1/2 and FIZZ1 are also commonly used markers." (PMID 41602451, 2026).
breast carcinoma (14 papers, 2016 to 2026). "Following on from the breast cancer predictions, HRH1 was found overexpressed in Tsc2‐deficient relative to wild‐type MEFs when exposed to serum‐reduced (0.5% FBS) media." (PMID 34378323, 2021). "Analyzing the lung‐metastatic breast cancer dataset that gave rise to the original metabolic predictions revealed an association between high HRH1 expression and lung metastasis." (PMID 34378323, 2021). "In the present study, we show that HRH1 is the major histamine receptor highly expressed in many cancer cell lines and cancer tissues and that coexpression of CXCR4 and HRH1 is associated with lower survival in breast cancer by analyzing publicly available RNA-seq databases." (PMID 36732336, 2023). "The role of HRH1 in breast cancer remains complex, and our findings reaffirm its ambiguous prognostic value." (PMID 41465279, 2025). "Specifically focusing on breast cancer, RNA-seq data showed that HRH1 mRNA levels were significantly downregulated in tumor tissues compared to normal tissues (p < 0.001)." (PMID 41465279, 2025). "Histamine synthesis, its mast-cell mediated release, and downstream cascades (cytokine and chemokine regulation) potentiated through histamine-receptors (e.g., HRH1) are dysregulated in ES and a plethora of cancers (including EC, breast cancer, etc.)." (PMID 40747097, 2025). "Here, we show that HRH1 is widely expressed in various cancer cell lines and cancer tissues and that coexpression of CXCR4 and HRH1 is associated with poor prognosis in breast cancer." (PMID 36732336, 2023). "According to several papers, histamine becomes an autocrine growth factor that regulates cell proliferation via HRH1 in experimental mammary carcinomas." (PMID 32340124, 2020). "Applying the Gene Set Analysis (GSA) we found that elevated expression of HRH1, EFNB1, KLK1, NRP2, and APP was associated with the basal-like subtypes of breast cancer as predicted by the MicMa cohort." (PMID 26673618, 2016). "To evaluate the clinical basis for this hypothesis, we first analyzed HRH1 expression and its prognostic value in breast cancer patient datasets." (PMID 41465279, 2025). "Hence, the HRH1 knockout or inhibition of HRH1 on macrophages with antihistamines reshaped the transcriptomic landscape of immune cells and blocked immune resistance when combined with anti-PD-1 treatment in mammary tumor and colon cancer mice models." (PMID 36189283, 2022). "Inhibiting HRH1 in basal and human EGFR 2 (HER2)-targeted therapy-resistant breast cancer cells can inhibit proliferation, activate mitochondrial apoptotic pathways, and enhance the effectiveness of HER2-targeted therapy." (PMID 40113769, 2025). "The interactions are visually represented in a diagram, showing that HRH1, HRH2, and HRH4 are central to the network, indicating their significant roles in breast cancer pathology." (PMID 39267843, 2024). "We propose that HRH1, NRP2, and STX1A can be used as prognostic biomarkers and therapeutic targets for basal and HER2-enriched breast cancer subtypes." (PMID 26673618, 2016). "High HRH1 expression levels were recently reported in different cancers including HCC, colorectal cancer (CRC), breast cancer (BC), melanoma, and non-small cell lung cancer (NSCLC) and were correlated with growth, metastasis, or therapeutic resistance of these cancer types." (PMID 40113769, 2025). "The role of histamine receptor H1 (HRH1) in breast cancer is complex and not fully elucidated." (PMID 41465279, 2025). "In addition, HRH1 and NRP2 should be considered interesting targets for the treatment of basal-related breast cancer subtypes, and STX1A could be an interesting target for the treatment of the luminal B and HER2-enriched subtypes." (PMID 26673618, 2016). "Therefore, therapies targeting HRH1, STX1A, and NRP2 might improve outcomes in basal-related breast cancer." (PMID 26673618, 2016).
breast carcinoma (continued). "Although other authors have already reported that HRH1 and NRP2 were involved in breast cancer development and progression, to our knowledge, the overexpression of these genes had not been correlated with basal-related breast cancer subtypes." (PMID 26673618, 2016).
Pruritus (13 papers, 2017 to 2025). Pruritus is an itch or a sensation that makes a person want to scratch. "Compound 48/80-induced acute pruritus is primarily associated with mast-cell degranulation and subsequent histamine release, which could be eliminated by antagonism of histamine receptor H1 and H4." (PMID 37122031, 2023). "The effects of BAs are prominent in patients suffering from chronic liver conditions, who develop pruritus from the activation of MAS Related GPR Family Member X4 (MRGPRX4) receptor expressed on dorsal root ganglion histamine receptor H1 (HRH1)-positive neurons by BA that have escaped the liver." (PMID 36816113, 2023). "Histamine H1 receptor (HRH1) plays a pivotal role in allergic inflammation and is considered a primary target for the pharmaceutical relief of pruritus." (PMID 28869563, 2017).
melanoma (11 papers, 2015 to 2025). A malignant, usually aggressive tumor composed of atypical, neoplastic melanocytes. "Several human trials showed that HRH1 antagonists (loratadine and desloratadine) can reduce risk and improve OS in patients with HCC, melanoma, and BC." (PMID 40113769, 2025). "Similar to the current findings, another cationic amphiphilic H1 antihistamine, terfenadine, was shown to induce cell death independently of HRH1 in melanoma cells." (PMID 39886963, 2025). "Terfenadine, an HRH1 antagonist, was reported to induce both apoptosis and autophagy in melanoma cells." (PMID 39886963, 2025). "Moreover, in melanoma, HRH1 inhibition delays tumor growth and prevents lung metastasis." (PMID 26673618, 2016). "In addition to HRH1, high concentrations of histamine were observed in various human malignancies such as CRC, BC, and melanoma." (PMID 40113769, 2025). "In tumor‐bearing mice, histamine was found to promote melanoma growth primarily through histamine receptor H1 (HRH1), rather than histamine receptor H2 (HRH2)." (PMID 41085102, 2025). "Recently, HRH1 was reported to shift macrophages toward an immunosuppressive M2 phenotype and suppress CD8+ T cell function, and additional treatment with antihistamines was found to amplify the effect of anti-PD1 antibodies in melanoma." (PMID 38715057, 2024).
Obesity (10 papers, 2010 to 2024). Accumulation of substantial excess body fat. "Loss of histamine receptor H1 (HRH1) impairs leptin control of food intake, leading to obesity." (PMID 20642857, 2010).